TNF (tumor necrosis factor)
Diseases named in the same sentence as TNF in open-access papers (continued):
Sharing a sentence is not in itself a finding about the gene and the disease.
glioma (388 papers, 2006 to 2026). A benign or malignant brain and spinal cord tumor that arises from glial cells (astrocytes, oligodendrocytes, ependymal cells). "The IL6-JAK-STAT3 and TNF-α signaling pathways via NF-κB were associated with the inflammation in glioma." (PMID 38985240, 2025). "Specifically, they are involved in the Hippo, ERK/MAPK, and tumor necrosis factor (TNF) signaling pathways, which are directly associated with glioma biology." (PMID 41011214, 2025). "Closely associated with TNF-α signaling is interleukin-1 beta (IL-1β), another critical pro-inflammatory cytokine involved in shaping the glioma microenvironment." (PMID 40565357, 2025). "We also investigated the effects of naringenin on modulating the inflammatory molecules IL-6, CCL2, and TNF-α associated with immunosuppression in glioma cells." (PMID 40149846, 2025). "While it can promote immune-mediated tumor clearance under certain conditions, sustained TNF-α activity is frequently associated with enhanced tumor cell migration, angiogenesis, resistance to apoptosis, and maintenance of glioma stem-like cells." (PMID 40565357, 2025). "In glioma, CNOT7 is overexpressed and associated with poor prognosis, contributing to glioma progression through TNF-α and IL6-JAK-STAT3 pathways." (PMID 41249119, 2025). "Wei and collaborators reported that the inhibition of TNFα secreted by glioma-associated macrophages (GAMs) inhibited the activation of endothelial cells, improving survival in a mouse glioma model and prolonging the durability of the response to AATx." (PMID 40565018, 2025). "Among the most prominent molecular drivers of glioma-associated inflammation is tumor necrosis factor-alpha (TNF-α), a pleiotropic cytokine that modulates various cellular processes, including proliferation, survival, differentiation, and immune responses." (PMID 40565357, 2025). "In our view, TNFα release from SorLA-deficient microglia promotes necroptosis of glioma cells and enhances neutrophil infiltration." (PMID 38499808, 2024). "At the same time, intracellular matrix metalloenzyme, one of the main reasons for glioma cells causing invasive damage, and the elevated cytokine interleukin-1 in Glioma β (IL-1 β) and tumor necrosis factor-α (TNF-α), are all overexpressed." (PMID 38651101, 2024). "The sorting receptor SorLA shapes the functional properties of glioma-associated microglia/macrophages by restraining TNFα release." (PMID 38499808, 2024). "Tumor-associated macrophages in glioma have been proposed to stimulate the proneural-to-mesenchymal transition through TNFα mediated NF-κB pathway activation." (PMID 38632238, 2024). "Classical inflammatory hallmarks (IFNα response and TNFα-signaling) were enriched in myeloid cells of pediatric IDH mutation gliomas, indicating the anti-tumorigenic phenotypes of these cells in the microenvironment." (PMID 38094301, 2023). "Cytokines IL-1β and TNF-α are generally recognized as inhibitors of glioma growth and associated with better prognosis." (PMID 36675073, 2023). "In parallel, glioma-associated macrophages are stimulated by glioma cells to produce tumor necrosis factor-α (TNFα), which activates the endothelial cell expression of the proangiogenic molecules (VCAM-1, ICAM-1, CXCL5, and CXCL10)." (PMID 35740307, 2022). "Their latest results indicate that the pro‐inflammatory cytokine expression of TNF, IL‐8, IL‐6 and NF‐κB is enhanced in glioma‐associated ECs." (PMID 33300633, 2021). "The expression levels of proinflammatory cytokines such as TNF-α and interleukin (IL)-6 in the inflamed brain and the blood of postsurgical U87 glioma-bearing mice were measured using commercial enzyme-linked immunosorbent assay (ELISA) kits." (PMID 30429468, 2018). "The present study investigated the phosphorylation of specific residues of NFκB is association with TNF-α-stimulated IL-6 synthesis in C6 glioma cells." (PMID 20205746, 2010).
glioma (continued). "Understanding the mechanism(s) of TNF-α mediated growth arrest will be important in unraveling the contribution of tissue associated macrophages in tumor resistance in gliomas." (PMID 17565690, 2007). "The results of the enrichment analysis revealed that the top ten significant KEGG pathways associated with the DEOSGs included MAPK, ErbB, GnRH, TNF, FoxO, the Fc epsilon RI signaling pathway, Kaposi sarcoma-associated herpesvirus infection, proteoglycans in cancer, bladder cancer, and glioma." (PMID 39125922, 2024). "To evaluate the combined impact of the developing glioma and SorLA loss from host cells on the tumor microenvironment, we first assayed the levels of selected cytokines (TNFα, MIP2, CCL5, CXCL1, IL1β, IL2, IL6, and IL10) in the tissue lysates derived from tumor-bearing and tumor-free hemispheres." (PMID 38499808, 2024). "This is the first time that GPCR has been linked to TNF in glioma." (PMID 37560473, 2023). "TNFAIP2 is a primary response gene of TNFα, and high expression is associated with increased cell proliferation, migration, invasion and metastasis in various cancers including breast and esophagus cancers and gliomas." (PMID 37511403, 2023). "The results showed that IgG, HCK, MHC-II, LCK, STAT1 interferon, B7-CD28, and TNF-related tumor immune responses were significantly enhanced with the increasing risk scores, indicating that the immune microenvironment in high-risk glioma patients regulates response changes." (PMID 37228500, 2023). "TNF-α/NF-κB signaling is closely associated with glioma proliferation." (PMID 35359663, 2022). "Inflammatory factors such as TNF‐α was reported to be significantly associated with the malignant progression of glioma cells and sustained activation of NFκB, which is caused by TNFα, leading to neuroblastoma recrudescence and regulation of cell invasion and metastasis." (PMID 34540695, 2021). "Therefore, the expression of IL‐8 and IL‐6 in the glioma‐associated ECs induced by TNF is blocked by the NF‐κB‐mediated pathway, which has important implications for anti‐angiogenesis therapy." (PMID 33300633, 2021). "Similarly, for TNF‐α, the pooled SMD was 1.80 (95% CI: 1.03‐2.56; P = .000), indicating that an elevated level of TNF‐α in the peripheral blood is significantly associated with an increased glioma risk." (PMID 31599129, 2019). "Moreover, a recent study suggested that TNF secretion by tumor-associated myeloid cells induces tumor-associated neutrophils with enriched proinflammatory factors that orchestrate immune-suppression and angiogenesis in glioma." (PMID 38561856, 2024). "Interestingly, a low plasma TNF-α level before surgery was associated with a high perioperative transfusion rate in glioma surgical patients, which may indicate that the preoperative immune response could influence perioperative transfusion requirements." (PMID 36765695, 2023). "Besides, AKT1, JUN, ALB, MAPK1, and TNF display good diagnostic value in glioma." (PMID 34873410, 2021). "Finally, although we conducted subgroup analyses for IL‐6, IL‐8, IL‐10, and TNF‐α with glioma risk to explore the potential sources of heterogeneity, high heterogeneity still existed in the studies of IL‐4, IL‐12, IL‐17, IL‐23, TGF‐β, and MCP‐1 based on the limited number of included studies." (PMID 31599129, 2019). "CBD/Mg-GAexhibits anticancer activity by significantly increasing ROS and suppressinganti-inflammatory signaling, as evidenced by reduced TNF-α levels.Mechanistically, it modulates NF-κB, thereby initiating apoptoticcascades in glioma cells." (PMID 41288593, 2026). "Targeting TNF-α signaling in gliomas has been challenging due to its dual role in tumor biology and host immunity." (PMID 40565357, 2025). "Secretion of TNF-α by TAMs, has been shown to be a crucial factor in inhibiting viral replication by inducing apoptosis in OV-infected glioma cells." (PMID 40061139, 2025).
glioma (continued). "In glioma, stem cells communicate with microglia via miRNA in extracellular vesicles, with miR-129-3p regulating IL-6, IL-8, and TNFα." (PMID 40248351, 2025). "Inflammatory and glioma cells express and can release SP that regulates neurogenic inflammation mediated by the release of IL-1β, IL-6, IL-8, TNF-α, GM-CSF, and LIF." (PMID 39941886, 2025). "Alteration of the key DNA methylation protein, DNMT3A, leads to increased proliferation and malignancy of human glioma through the TNF-α-NF-kB signaling pathway." (PMID 42135822, 2025). "This, in turn, enhances the transcription of tumor necrosis factor-α(TNF-α), subsequently activating the NF-κB signaling pathway and facilitating glioma progression." (PMID 40710326, 2025). "Increased astrocyte reactivity, triggered by direct interactions with glioma cells, can alter the tumor microenvironment by producing inflammatory factors such as IFNα and TNFα, among others." (PMID 40565018, 2025). "In gliomas, TNF release induces neovascularisation via VEGF and T cell depletion via the activation of immunosuppressive macrophages." (PMID 41034696, 2025). "Glioma-derived cytokines, including tumor necrosis factor-alpha (TNF-α), interleukins (ILs): IL-1α and IL-1β, IL-4, IL-6, and IL-8, play pivotal roles as inflammatory mediators." (PMID 40061139, 2025). "Specific factors within the glioma microenvironment, notably tumor necrosis factor-α, and ceruloplasmin, actively attract and stimulate neutrophils to migrate toward and infiltrate glioma tissues." (PMID 39911305, 2025). "Ca2+‐ATPase activity in membranes from human glioblastoma (U‐251, U‐138) and rat glioma (C6) cell lines, untreated (Control) and treated with cytokines (3 ng·mL−1 of IL‐1α, 30 ng·mL−1 of TNF‐α, and 400 ng·mL−1 of C1q), or with 5 μm Aβ1‐42 or 10 nm tau." (PMID 40325855, 2025). "This interpretation is supported by previous studies showing that TNF-α signaling can reduce stemness by promoting differentiation or senescence-like states in glioma and other cancers." (PMID 40806540, 2025). "Inflammatory markers like IL-6, CRP, SAA, and TNF-α can induce M2 macrophage polarization, promoting glioma progression and playing an essential role in glioma development." (PMID 41244525, 2025). "In our study, for the first time, the FASN inhibitor CER reduced the levels of p-PI3K (a lipid kinase family member), p-AKT, NF-κB p65 active subunit, and TNF-α in human glioma cells." (PMID 40133683, 2025). "The inflammatory hallmarks TNF-α signaling via NF-kB, allograft rejection, and complement have been observed to be enriched in human glioma tissue." (PMID 42135822, 2025). "Chronic inflammation is increasingly recognized as a driver of glioma progression, with tumor necrosis factor-alpha (TNF-α) playing a central role in modulating the tumor microenvironment." (PMID 40565357, 2025). "Glioma cells secrete IL-8 and CCL2 and induce glioma-associated macrophages (GAMs) to secrete TNF-α, which induces endothelial cell activation to promote tumor survival." (PMID 42135822, 2025). "For example, TNF-α/NF-κB activation has been shown to induce astrocytic differentiation and suppress glioma stem-like cell phenotypes, as well as trigger senescence-associated transcriptional programs under inflammatory conditions." (PMID 40806540, 2025). "Emodin effectively inhibits glioma (U251) cell proliferation, inducing apoptosis and necroptosis via the TNF-α/RIP1/RIP3 signaling axis." (PMID 40490812, 2025). "On the other hand, studies have demonstrated that IL-6 and TNF-α contribute to glioma cell proliferation, invasion, and migration." (PMID 40149846, 2025). "This concept is exemplified by oncolytic HSV-1 inducing TNF-alpha-mediated glioma cell death, with transient TNF-alpha blockade being able to enhance both viral replication and mouse survival." (PMID 40240536, 2025). "No remarkable differences were detected in the levels of NF-κB and TNF-α between high and low-grade gliomas." (PMID 40809181, 2025).
glioma (continued). "Although the role of inflammation in tumor biology remains a matter of debate, depleting TNFα in host cells resulted in larger tumors and shorter survival in the murine glioma model." (PMID 38499808, 2024). "Meanwhile, cytokines secreted by gliomas can suppress the expression of tumor necrosis factor-α (TNF-α) and major histocompatibility complex (MHC II) by microglia in vivo or in vitro, thereby weakening their ability to present antigens to T cells." (PMID 39143438, 2024). "Further investigation into TNF-α’s effect on NF-κB activation in glioma cells confirmed activation via Western blot detection of phosphorylated NF-κB." (PMID 39769099, 2024). "Regarding TNF signaling, resveratrol reduces TNF-α-induced glioma cell invasion by inhibiting NF-κB activation and downregulating urokinase plasminogen activator (uPA) expression." (PMID 39769099, 2024). "MiR-18a downregulates RORα through the TNF-α-mediated NF-κB signaling pathway, inhibiting glioma proliferation and tumor development." (PMID 38725854, 2024). "To validate findings from the bioinformatics analysis regarding neuroinflammation, we stimulated glioma cells with TNF." (PMID 38561856, 2024). "In this context, targeting SORL1 expression in GAMs or the interaction between SorLA and TNFα emerges as an exciting strategy for future pharmacological interventions in glioma." (PMID 38499808, 2024). "Our study has identified CSMD1 as a tumor suppressor in gliomas and elucidated its role in TNF-induced neuroinflammation, contributing to a deeper understanding of glioma pathogenesis." (PMID 38561856, 2024). "Within gliomas, the TNF signaling pathway is recognized as a pro-tumor mechanism that aids in tumor cell evasion of apoptosis and promotes immunosuppression within the tumor microenvironment." (PMID 38560169, 2024). "Subsequently, glioma cells were treated with 10 ng/mL TNF-α and varying RSV concentrations (5, 10, and 20 μM) for 24 h." (PMID 39769099, 2024). "We subsequently quantified the levels of IL-6 and IL-8 secreted in the supernatant using ELISA after two hours of TNF treatment of glioma cells, as STAT3 was observed to be upregulated at that time point." (PMID 38561856, 2024). "In line with this notion, inhibition of STAT3 in a murine model of glioma enhanced TNFα expression in microglia/macrophages, blocked tumor growth and improved survival." (PMID 38499808, 2024). "A Western blot analysis performed on subfractionated U-118 and U-87 glioma cells following TNF treatment demonstrated that pP65-Ser536 was upregulated in the cytoplasmic fraction of Ctrl clones compared to CSMD1-overexpressing clones." (PMID 38561856, 2024). "The results showed that the mRNA expression levels of STAT3 (P < 0.01), IL-6 (P < 0.01), and TNF-α (P < 0.01) were significantly increased in glioma samples compared with paracancerous tissues." (PMID 38495483, 2024). "Initially, glioma cells were exposed to varying TNF-α concentrations (1–20 ng/mL) for 24 h, and a Matrigel assay identified 10 ng/mL as the concentration inducing the highest invasion level." (PMID 39769099, 2024). "The findings of the study showed that TNF-α prevents proliferation and induces apoptosis in glioma cells." (PMID 37280571, 2023). "IL-1β coordinates the progression of neuroinflammation by upregulating the expression of other pro-inflammatory cytokines, whereas TNFα induces the expression of vascular endothelial growth factor in gliomas, leading to increased angiogenesis seen in GBM." (PMID 38003396, 2023). "GD2-CAR/NFATsyn-IL-12 T-cells readily killed GD2+ patient-derived glioma spheroids and secreted IL-12, TNF-α, IFN-γ, Il-2, perforin, and granzyme B upon coculture with GD2+ glioma cells." (PMID 38136398, 2023). "The secretion of TNF-α by TAMs in response to OV therapy has been shown to be a crucial factor in inhibiting viral replication by inducing apoptosis in OV-infected glioma cells." (PMID 37234776, 2023).
glioma (continued). "A previous study reported that elevated circulating levels of IL-6, IL-8, IL-17, TNF-α, TGF-β, and CRP are significantly linked to an increased risk of glioma." (PMID 38259287, 2023). "The resistance of human glioma cells to Fas/APO-1 antibody-mediated apoptosis was mainly associated with a low level of Fas/APO-1 expression, but cytokines IFN-γ and TNF-α enhanced the sensitivity to Fas/APO-1-mediated killing." (PMID 37671057, 2023). "Levels of IL-1β and TNF-α were significantly increased in sensitive individuals, indicating the immunosuppression induced by glioma was reversed in sensitive mice." (PMID 36927689, 2023). "Multiple studies have shown that curbing TNF-α secretion in gliomas can effectively increase viral replication and spreads, thereby improving the anti-tumor effects in OV therapy." (PMID 37234776, 2023). "In conclusion, TNF modulates the anti-tumor immune response through various mechanisms, establishing its significance in glioma immunotherapy." (PMID 38259287, 2023). "To identify TNF associations in GBM patients, we performed bioinformatics analysis of public databases - The Cancer Genome Atlas (TCGA) and the Chinese Glioma Genome Atlas (CGGA)." (PMID 37153654, 2023). "Results demonstrated that, when cocultured with DHX9‐overexpressed glioma cells, macrophages exhibited decreased expression of M1 markers (IL‐1b, IL‐12b, and TNF‐α) and increased expression of M2 markers (IL‐10, CD163, and ARG1)." (PMID 36377508, 2023). "TNF-α and IL-1β are pro-inflammatory cytokines that are found in supratentorial high-grade gliomas and are involved in neuroinflammation, gliomagenesis, and development of radio-resistance." (PMID 37752585, 2023). "In the first 24 h, glioma-neutrophil cultures produced high amounts of IL-8 and TNFα, slightly increased amounts of IL-12p70, and low to zero levels of IL-1β, IL-6, and IL-10." (PMID 37292196, 2023). "A co-culture system with CD8+ T cells and glioma cells decreased the proliferation of AP-2α-overexpressing U87 cells, but increased Ki67 expression and cytokines TNFα and IFNγ secretion, decreased PD-1 levels in CD8+ T cells in vitro." (PMID 37330579, 2023). "In fact, the NK cells can modulate the growth of the glioma via sensing growth factors and secreting interferon gamma and tumor necrosis factor alpha." (PMID 35668574, 2023). "Only tumour necrosis factor alpha (TNF-α) and TNF receptors have been explored pre-diagnostic bloods of glioma patients." (PMID 37265788, 2023). "Nevertheless, TNF-α was observed to promote glioma cell motility and invasion by activating NF-κB, by increasing mRNA expression of uPA and uPAR genes in the U373MG cell line, and by modulating VEGF and IL-8 gene expression in the U251MG cell line." (PMID 36675073, 2023). "Let-7 miRNA directly activates TLR7 in microglia, leading to upregulation of MHC I and ICAM1 (CD54) and induction of TNF-α production to inhibit glioma growth." (PMID 37700840, 2023). "In vitro α-MSH and ACTH1–24 inhibits the production of TNF-α, IL-6, and NO in cultured murine microglial cell lines and also inhibits TNF-α production in human glioma cell lines." (PMID 37047638, 2023). "Using LPS-treated human glioma cell lines and murine brain inflammation models, thiopental was reported to exert anti-inflammatory effects with the suppression of TNF-α production by inhibiting NF-κB pathway activation." (PMID 36765695, 2023). "A significant TNFα inhibition by both KPFs on the glioma cell lines evaluated was observed, and only KPF-BBR was able to significantly inhibit IL-1β on the NG-97 cells." (PMID 37445894, 2023). "TNF‐α, an inflammatory factor, is considered to be remarkably related to the malignant progression of gliomas, and NFκB sustainedly activated by TNF-α results in invasion and metastasis of tumor cells." (PMID 37004060, 2023). "Recent data suggested SLC39A7 to promote glioma cell malignancy through the TNF-α-mediated NF-κB pathways." (PMID 36142814, 2022).